EGR3 (early growth response 3)
Diseases named in the same sentence as EGR3 in open-access papers (continued):
Sharing a sentence is not in itself a finding about the gene and the disease.
cancer (31 papers, 2009 to 2025). A tumor composed of atypical neoplastic, often pleomorphic cells that invade other tissues. "Hence, the positive association of EGR3 gene expression with CAFs in these cancers suggests the contribution of this gene to promoting the immunosuppressive roles of CAFs, while negative correlations obtained for Tregs in DLCBCL would suggest the reverse." (PMID 35201514, 2021). "Our results suggest that Egr3 may act both as a diagnostic marker (increased expression in cancer compared to normal) and as a prognostic marker that may distinguish between aggressive and non-aggressive tumors (differentially expressed in non-relapse and relapse)." (PMID 23342084, 2013). "Among them, EGR3 has been less extensively studied in cancer biology despite its established function in neurodevelopment and psychiatric disorders, such as schizophrenia and bipolar disorder." (PMID 40649712, 2025). "Future research employing integrative multi-omics approaches across defined cancer subtypes will be critical to identify shared and unique EGR3-driven pathways, ultimately informing context-appropriate therapeutic strategies." (PMID 40649712, 2025). "EGR3: While recognized as a stress-response transcription factor in neurodegeneration, its role in cancer remains contentious." (PMID 41472745, 2025). "The lentivirus-mediated EGR3 knockdown in CHMp cells showed higher tumorigenicity, as evidenced by significant increases in cancer cell growth and migration." (PMID 38338065, 2024). "All the other genes (ATF3, EMP1, GADD45B, SOCS3, and ZFP36), distinct from EGR3, have been independently demonstrated to function as migration inhibitors in cancer cells." (PMID 38543002, 2024). "EGR3 can regulate the expression of these genes to affect the sensitivity of cells to 5-fluorouracil, thereby affecting the efficacy of cancer treatment." (PMID 39399504, 2024). "Several studies demonstrated that EGR3 plays a role in cancer cell migration and invasion, indirectly influencing cancer progression." (PMID 38338065, 2024). "Recently, several studies have shown that the expression of EGR3 was frequently dysregulated in a variety of cancer types." (PMID 34722264, 2021). "Here, we report the increased expression of AP-1, ATF2, REST, and EGR3, all transcription factors involved in cancer cell invasive behavior." (PMID 30813636, 2019). "Both normal and cancer samples exhibited Egr3 staining of the prostate glands; however the cancer samples had a significantly higher number of pixels strongly labeled with Egr3 antibody." (PMID 23342084, 2013). "Although the amount of literature detailing Egr3 regulation of inflammatory genes is small, previous observations show that the NFκB-Egr3 complex has the potential to regulate many inflammatory genes important to cancer." (PMID 23342084, 2013). "EGR3 activates related inflammatory signaling pathways (such as the NF-kb pathway) by activating the expression of IL-6 and IL-8, which are closely related to the occurrence and development of cancer." (PMID 31844579, 2019). "In contrast, the ten node genes in the mammary glands of the offspring of dams fed the CON diet were linked to changes in the expression of genes indicative of reduced cancer risk (downregulation of DPF3, SNORA41) and improved immune functions (upregulation of ZBP1, ZFP683; downregulation of EGR3)." (PMID 28673325, 2017). "Much work remains to be done, however, on unraveling the role of Egr3 in other types of cancer." (PMID 23342084, 2013). "The MAF oncogene, HOP, RORA and EGR3 from the same cluster directly participate in the regulation of growth, and as a consequence may be better markers of cancer differentiation status." (PMID 19888454, 2009). "Moreover, EGR3 is identified as a direct target of microRNAs regulating cancer development." (PMID 38338065, 2024).
cancer (continued). "Additionally, the alteration in the expression of EGR3 has been associated with survival rate and time to first treatment (TTFT), thus suggesting that EGR3 can serve as a prognostic biomarker in various types of cancer." (PMID 38338065, 2024). "Although this study supports the role of EGR3 as an oncogenic driver in GBM by promoting cell growth and upregulating MYC and CDK1, its function in cancer appears to be complex and context-dependent." (PMID 40649712, 2025). "Whereas there are nine rhythm genes (MTNR1B, NR1D1, RORB, RORA, OPN4, C1orf51, PROK2, SERPINE, and EGR3) that are differently expressed in the high and low MSI group in more than 1/3 cancer types." (PMID 31927791, 2020). "We identified 15 highly connected hub genes in MEtan, including ABCA8, AFP, EGR3, EXO1, HMGA1, MT1X and VARS, which play roles as major regulators in cell-cycle regulation and cancer development." (PMID 27220887, 2016). "Egr3 knockout mice have not yet been utilized to study the role of the transcription factor in cancer, however recent reports have used cell culture models and gene expression data to study Egr3 function in several areas important to cancer." (PMID 23342084, 2013).
infection (9 papers, 2016 to 2025). The state of being infected such as from the introduction of a foreign agent such as serum, vaccine, antigenic substance or organism. "Consistent with our sequencing results, the genetic backgrounds of the egr1 and egr3 alleles were previously noticed to harbor anomalies that led to egr-independent susceptibility to infection by Gram-positive bacteria." (PMID 33127847, 2020). "These NimC1 mutations are recessive, and we speculate that their presence on each egr mutant chromosome in our experiments might explain the transient accumulation of dying cells; perhaps they also account for the infection susceptibility found previously in egr3 mutants." (PMID 33127847, 2020). "We identified ten NK subgroup-specific marker molecules (Kcnj8, Cmah, Ccnd2, Cx3cr1, Thy1, Tnfrsf9, Zbtb20, Gng11, CD226, Egr3) from C0 to C9 and assessed their expression changes during infection using RT-qPCR." (PMID 40244063, 2025). "TRBV6-5 and BCL11B are primarily implicated in the immune response post-infection; PTGDS, EGR3, and CXCR5 modulate the host’s inflammatory response." (PMID 39591343, 2024). "EGR1 expression significantly increased 18.5-fold (p < 0.01) at 2 h, peaking at 20.1-fold (p < 0.01) by 4 h post-infection, whilst EGR3 gene expression increased 15.8-fold (p < 0.05) at 2 h, increasing further to 32.5-fold (p < 0.0001) by 4 h post-infection." (PMID 39635778, 2024). "In contrast, four (ULBP1, EGR3, RAET1K, EGR2) genes were downregulated in uninfected cells (GFP- pHrodo-) relative to the other three infection outcomes." (PMID 40630957, 2025). "By combining transcriptome analysis and machine learning, we identified four key targets related to VVTT infection in A293 cells: ARC, JUNB, EGR3, and FOS." (PMID 39940969, 2025). "We found that 172 transcripts were differentially expressed in response to T. gondii infection of villous explants, with 22 of these transcripts also being differentially expressed in response to infection of PHT cells, which included EGR3, EGR4, and CCL22." (PMID 29317509, 2018).
psychiatric disorder (4 papers, 2016 to 2024). A disorder characterized by behavioral and/or psychological abnormalities, often accompanied by physical symptoms. "Psychosis-like phenotypes and hyperactivity observed in these EGR3-deficient mice could be reversed with antipsychotic drugs used in treatment of psychiatric disorders, providing an additional support for these findings." (PMID 29459824, 2018). "We have hypothesized that both Bdnf and Egr3 are crucial components of a biological pathway implicated in mental illness risk." (PMID 29867393, 2018). "Considering that EGR3 translates environmental stimuli into long-term changes in the brain, disruption in biological pathways involving EGR3 may induce an impaired response to stress and influence on risk for psychiatric disorders, particularly BD." (PMID 27163206, 2016). "Together, these findings suggest that disruption of Egr3 activity, or function of other proteins that act either upstream or downstream in the EGR3 pathway, may mediate both the genetic and environmental factors that contribute to risk for severe mental illnesses." (PMID 29867393, 2018). "This means that changes in EGR1 and EGR3 expression could potentially influence the activity of several biological pathways involved in the pathophysiology of psychiatric disorders." (PMID 38219212, 2024).
hematologic malignancies (1 paper, 2023). "Accordingly, our study and these data imply the limitation of EGR3 expression to be concomitant with a differentiation block of the B-lineage in hematologic malignancies." (PMID 37100882, 2023).
neurodegenerative disease (1 paper, 2022). A disorder of the central nervous system characterized by gradual and progressive loss of neural tissue and neurologic function. "In total, these findings suggest that altered EGR3 activity, or disruption of proteins that function upstream or downstream of EGR3, may increase risk for neuropsychiatric disorders and play a role of development of neurodegenerative disease." (PMID 35941129, 2022).
neurological diseases (1 paper, 2024). "MBD5, OGDHL, AUTS2, EGR3, QPCT, and ITGA8 are linked to neurological diseases." (PMID 39588153, 2024).
EGR3 also shares sentences with these, for which no sentence is quoted: Alzheimer’s dementia (2 papers); Alzheimer’s disease (2); colorectal cancer (2); coronary artery disease (2); COVID-19 (2); ovarian carcinoma (2); Ataxia (1); atherosclerosis (1); bladder urothelial carcinoma (1); brain ischemia (1); chronic lymphocytic leukemia (1); Cirrhosis (1); congenital heart disease (1); congenital hypothyroidism (1); developmental delay (1); esophageal tumor (1); fibrosis (1); Gait ataxia (1); glaucoma (1); head and neck cancer (1); Hepatitis B (1); Hip dysplasia (1); infarction (1); keloid (1); lymph node metastasis (1); lymphoma (1); mast cell leukemia (1); metabolic disorders (1); neuroblastoma (1); posterior uveitis (1).
A further 1 disease shares a sentence with EGR3 in 1 paper.